TNF (tumor necrosis factor)
Diseases named in the same sentence as TNF in open-access papers (continued):
Sharing a sentence is not in itself a finding about the gene and the disease.
asthma (continued). "Gene-set enrichment analyses revealed that epigenomic modifications of albuterol could participate in asthma-relevant processes (e.g., IL-2, TNF-α, and NF-κB signaling pathways)." (PMID 37784136, 2023). "TNFα and IFNγ are known to synergistically induce the production of several pro-inflammatory cytokines and chemokines, including CXCL10, a key T lymphocyte chemoattractant implicated in severe asthma." (PMID 35578269, 2022). "Moreover, EMT protein and TL1A/DR3 axis expression synchronously decreased after mice with OVA-induced asthma were treated with infliximab by neutralizing TNF-a activity." (PMID 35359966, 2022). "In this context, the list of proteins and pathways defined in this study may be valuable to design new interventions to specifically target the combinatorial effect of IL-17A/F and TNF-α for the control of severe asthma." (PMID 36517803, 2022). "Elevated levels of inflammation-related factors such as IL-6, C-reactive protein, and TNF-α are found in obese pregnant women, which may contribute to the development of wheezing and asthma in children." (PMID 37780583, 2022). "In a mouse model, TNF-α was involved in glucocorticoid insensitivity in neutrophilic inflammation in asthma, which may induce chronic inflammation and lead to airway remodeling." (PMID 35626330, 2022). "Thus, the present study had a sufficient theoretical basis to assess the effect of IL-35 in asthma using TNF-α-induced bronchial epithelial cells as a model." (PMID 35034554, 2022). "Similarly, serum TNF-α levels have also been reported as elevated in the serum and bronchoalveolar lavage fluid of patients with severe compared with mild asthma and healthy controls." (PMID 35807067, 2022). "We first induced BEAS-2B cells with TNF-α to simulate the injury induced by TNF-α in asthma." (PMID 35000533, 2022). "For example, TNF-α and IL-1β synergize to promote airway hyperresponsiveness, which might partly underlie the role of TNF-α in asthma." (PMID 35281022, 2022). "Increased levels of tumor necrosis factor (TNF) α have been linked to several pulmonary inflammatory diseases, including asthma, chronic obstructive pulmonary disease (COPD), acute lung injury (ALI), acute respiratory distress syndrome (ARDS), sarcoidosis, and IPF." (PMID 35672815, 2022). "It was found that the levels of these three substances were significantly reduced, indicating that puerarin could inhibit NF-κB and TNF-α pathways, which has played a role in the treatment of asthma." (PMID 36358493, 2022). "Leptin also influences inflammatory responses by inducing the activation of monocytes and both CD4+ and CD8+ T cells, and the production of pro-inflammatory cytokines such as TNF-a or IL-18, which may affect different respiratory diseases, including asthma." (PMID 36613991, 2022). "Interestingly, we found that most of the cytokines (IL-12p70, IL-13, IL-4, IL-6, TNF-α, and IL-8) in the asthma patients tend to increase when the low expression of eosinophils; but in the ACO group, only INF-γ and IL-10 showed an increase." (PMID 36311545, 2022). "However, the IL-1β level in lung tissue homogenates and the TNF-α level in BALF were significantly higher in the asthma and ACO-a models than in the control." (PMID 36474247, 2022). "The protein targets identified in this study will be useful for the development of interventional strategies to target biological processes enhanced by the concurrent presence of IL-17A/F and TNF-α, relevant to chronic respiratory diseases such as steroid-unresponsive severe asthma." (PMID 36517803, 2022). "Besides, TNF-α released from a variety of cells (such as mast cells and macrophages) in airways increased in the asthma model group." (PMID 35600943, 2022). "Therefore, in this study, a model of TNF-α-induced bronchial epithelial cell injury was used to investigate the mechanism of action of IL-35 to inhibit cell pyroptosis and thereby reduce asthma injury." (PMID 35034554, 2022).
asthma (continued). "Seven hypermethylated (CCL11, TNF, IL5, CCL2, CXCL1, CCL8, IL17RB) mRNAs (>twofold compared with control) were finally selected, as their mRNAs have been clearly reported as being associated with asthma." (PMID 36250525, 2022). "Notably, the research on asthma inflammation using TNF-α-induced bronchial epithelial cells as a model has been reported." (PMID 35034554, 2022). "Therefore, the current study assessed the alterations in OS, TNF-α, and ED biomarkers in children with asthma and pneumonia, children with pneumonia only, and healthy children." (PMID 36076196, 2022). "TNF-α along with IL-17 family of cytokines, including IL-17A/F, is enhanced in severe asthma." (PMID 36517803, 2022). "While the pathways that mediate corticosteroid insensitivity in asthma remain poorly defined, recent studies suggest that enhanced Th1 pathways, mediated by TNFα and IFNγ, may play a role." (PMID 35578269, 2022). "Animal models in which OGG1 has been shown to promote inflammation include contact hypersensitivity (skin inflammation;), endotoxin shock (generalized, “whole body” inflammation), asthma, Pseudomonas infection, hypoxia-reoxygenation-induced neuroinflammation and TNF-induced lung inflammation." (PMID 36289805, 2022). "A summary of the role of TNF-α in the pathogenesis of asthma has been reported and suggested that slowing disease progression and suppressing inflammation could be achieved by blocking the production or inhibiting the action of TNF-α." (PMID 35034554, 2022). "Although studies revealed that SMD can attenuate asthma by regulating the expression of inflammatory mediators such as of INF-γ, IL-4, IL-10, IL-13, and TNF-α, the exact mechanism underlying its protective effect remains unclear." (PMID 36578267, 2022). "This study identifies proteins and signaling mediated by concurrent IL-17A/F and TNF-α exposure in the lungs, relevant to respiratory diseases characterized by chronic inflammation, especially neutrophilic airway inflammation such as severe asthma." (PMID 36517803, 2022). "Moreover, Th1 cells, Th17 cells, ILC1s, ILC3s, and M1 macrophages are involved in this endotype, and their production IL‐1β, IL‐6, IL‐17, IFN‐γ, and TNF‐α are responsible for the recruitment and activation of inflammatory cells during asthma attacks." (PMID 36051916, 2022). "The present study aims to reveal the detailed mechanism in TNF-α-stimulated BEAS-2B cells by which TXL might exert effects on the development of asthma." (PMID 35000533, 2022). "In Th2-low asthma, IL-17 and TNF-α promote the recruitment of neutrophils to the lungs." (PMID 36078171, 2022). "Interleukin (IL) -5 levels were significantly higher in patients with ABPA than in those with CPA, and IL-33 and tumor necrosis factor (TNF) levels were significantly higher in patients with CPA than in those with asthma (p < 0.05, Dunn’s multiple comparison test)." (PMID 35628692, 2022). "In a meta-analysis of 34 studies involving 5,477 asthma patients and 5,962 controls TNF-α rs1800629 (no overlap) polymorphism was only significantly associated with asthma risk in Asian populations, but not in Caucasian populations." (PMID 36151579, 2022). "It has been proposed that the bidirectional association between asthma and SBD is due to inflammation in the “united airway,” for example, those with uncontrolled asthma have been found to have higher levels of tonsil TNF‐α compared to children with well‐controlled asthma." (PMID 35861116, 2022). "Additionally, ganoderic acid C1 in the ASHMITM herbal formula comprising Ganoderma lucidum Sophora flavescens and Glycyrrhiza uralensis has been reported to have potential for treating TNF-α mediated inflammation in asthma and other inflammatory diseases." (PMID 35630531, 2022). "Recent advances in our understanding of asthma pathogenesis suggest that both IL-6 and TNF may represent potential targets for treatment of severe neutrophilic asthma." (PMID 35408882, 2022).
asthma (continued). "In severe asthma, although the heterodimer IL-17A/F is known to interplay with other cytokines enhanced in the lungs such as TNF-α, the downstream targets, signaling intermediates and functional outcomes of this interaction remain largely unknown." (PMID 36517803, 2022). "TNF-α is elevated in the serum of asthma patients and correlates with poor ventilation." (PMID 35266441, 2022). "Kaempferol, a plant flavonoid, and its glycosylated derivative, kaempferol-3-O-rhamnoside (K-3-rh), have the potential for anti-inflammatory, antioxidant, and anti-asthmatic effects in an asthma model mouse by diminishing inflammatory cells, IL-4 and IL-13, TNF-α as well as IgE immunoglobulin." (PMID 35889525, 2022). "Notably, the present study found that TNF-a was closely associated with TL1A/DR3 in asthma, and the TL1A/DR3 targets play a key role in EMT induced by TNF-a." (PMID 35359966, 2022). "Th2-low asthma can be mediated by non-Th2 cytokines, including IL-17 and tumor necrosis factor-α." (PMID 36078171, 2022). "The TNF-α level was higher in the ACO-a model than in the asthma model." (PMID 36474247, 2022). "TNF-a expression remarkably increased in the asthma model compared with the control." (PMID 35359966, 2022). "In the current study, we hypothesized that combined IL-6/TNF inhibition may be beneficial in the context of severe asthma." (PMID 35408882, 2022). "In T2 asthma, the Th2 cytokines IL-4, IL-5, IL-9, IL-13, and IL-25, and the acute proinflammatory cytokines TNF-α, IL-1β, IL-6, and IL-8, subsequently lead to bronchial hyperresponsiveness (BHR), and plasma cells and antibody-producing cells secrete antibodies." (PMID 36430662, 2022). "This trend may explain the finding that during the atypical course of asthma and its resistance to standard glucocorticosteroid therapy, anti-TNF therapy is sometimes effective and is typically used against RA specifically." (PMID 36611799, 2022). "In patients with severe steroid-resistant asthma, the expression of tumor necrosis factor (TNF)-α in the lung was significantly increased and could not be inhibited by GCs." (PMID 35600871, 2022). "In addition, in clinical study, asthma patients who received anti-TNF-α treatment showed improvement in quality of life, lung function and airway hyper-responsiveness." (PMID 35034554, 2022). "The protective activities of SPM are also observed with phagocytes from patients with asthma whereby AT-RvD1 reduced TNF-α levels in peripheral blood mononuclear cells from patients with severe asthma stimulated with lipopolysaccharide or Dermatophagoides pteronyssinus." (PMID 35327544, 2022). "Therefore, the present study used a TNF-α-induced bronchial epithelial cell injury model to investigate the mechanism of IL-35 action on cell pyroptosis and asthma injury." (PMID 35034554, 2022). "Asthma appears to be a definite but rare side effect of the anti-TNF blockade." (PMID 35163689, 2022). "Moreover, the inflammation promoted by adipocytes has been increased in obese subjects with asthma due to the release of pro-inflammatory mediators, such as IL-6, TNF-a, or leptin, and the downregulation of anti-inflammatory factors, including adiponectin." (PMID 36613991, 2022). "Results showed adequate adherence was associated with lower levels of CRP, IL-6, and TNF-α, and soluble vascular cell adhesion molecule-1 (sVCAM-1) in healthy males and females, and IL-17 in both males and females with asthma." (PMID 34825233, 2021). "Serum TNF represents an important biomarker for severe asthma." (PMID 34084159, 2021). "Interestingly, treatment with the anti-TNFα etanercept improves airway hyperresponsiveness and quality of life in refractory asthma, and this improvement positively correlated with etanercept-induced reduction of membrane-bound TNFα expression." (PMID 34658882, 2021). "Notably, the TNF, TLR and NF-kappaB signaling pathways are classically associated with inflammation, and play critical roles in the pathogenesis of asthma." (PMID 33645621, 2021).
asthma (continued). "Therefore, we measured IL-1β, IL-6, and TNF-α levels to indirectly verify the maturity of DCs in patients with asthma." (PMID 33503170, 2021). "Anti-TNF biologics as therapeutics for severe asthma were tested in a number of clinical studies." (PMID 34084159, 2021). "Therefore, blocking this cytokine in severe asthma initially appeared promising, and administration of anti-TNF reagents demonstrated encouraging results in animal asthma models." (PMID 34084159, 2021). "TNF-α expression increased in PBMC in parallel with BMI increase in subjects with asthma." (PMID 33418879, 2021). "IL-6 and TNF are the important inflammatory mediators in the pathogenesis of asthma." (PMID 34084159, 2021). "Furthermore, the MAPK signaling pathway can control the expression of inflammatory factors (IL-6 and TNF-α) to regulate inflammation and immune responses in asthma." (PMID 34880921, 2021). "The airway tissue produces several bioactive molecules, including IL-8 and TNF-α, collectively called adipokines, which affect inflammatory sensitivity and may have a powerful role in developing asthma." (PMID 34621380, 2021). "IL-37 attenuated the development of IL-1β, IL-6, and TNF-α in sputum cells (LPS-stimulated) in asthma patients and caused suppression of IL-17 production more notably in patients with asthma than in healthy controls." (PMID 34516405, 2021). "Preliminary data suggests that combined pharmacological inhibition of TNF and IL-6 during asthma may be more efficient as compared to individual neutralization of these cytokines." (PMID 34084159, 2021). "Inhibition of TNF-α can significantly reduce the imbalance of metalloproteinases in asthma." (PMID 34248632, 2021). "The TNF-α is also included in the initiation of allergic airway responses in asthma." (PMID 34249177, 2021). "In severe asthma, especially in patients resistant to glucocorticoid therapy, the M1 macrophage phenotype predominates, producing numerous pro-inflammatory mediators, such as TNF-α, IL-1β and NO, which aggravate lung injury and accelerate airway remodeling." (PMID 34281592, 2021). "The enrichment analysis of GO and KEGG pathways found that the treatment of asthma by PRA may be related to the process of TNF (tumor necrosis factor) release, which can regulate and inhibit multiple signaling pathways such as ceramide signaling." (PMID 34557554, 2021). "Since TNF induces pentraxin-3 secretion and the later promotes the secretion of eotaxin-1/CCL11, it is legitimate to speculate that pentraxin-3, in an autocrine manner, mediates some of the effects of TNF in asthma." (PMID 35387000, 2021). "Further cluster and enrichment analysis suggested that NF-κB signaling pathway, PI3K/Akt signaling pathway, IL-17 signaling pathway, Toll-like receptor signaling pathway, and TNF signaling pathway might be core pathways of ZOL for asthma." (PMID 32015750, 2020). "This and the activation of congenital type 2 lymphoid cells (ILC2s) could explain why elevated T2 cytokines such as IL-4 and IL-5 are found in asthma in parallel to an increase in TNF-α." (PMID 33134805, 2020). "One and 5 μg/ml BioPM collected from chicken, goat and pig farms induced the production of IFNγ, IL-10, IL-1β and TNFα by PBMCs from stable asthma patients and healthy volunteers in an apparent concentration-dependent manner (except for TNFα production induced by BioPM from the goat farm)." (PMID 32620109, 2020). "TNFα is also of interest in the context of asthma as it was reported to determine the severity of hyperresponsiveness and contribute to an exaggerated inflammatory response by bronchial epithelial cells from most asthma patients in the presence of IL-17." (PMID 32620109, 2020). "TNF-α and IL-6, highly expressed in the asthmatic subjects, are important pro-inflammatory cytokines in regulating asthma pathophysiology." (PMID 32929606, 2020). "TNF-α and IL-6 are major pro-inflammatory cytokines involved in asthma." (PMID 32929606, 2020).
asthma (continued). "Ghrelin is expected to have anti-inflammatory actions that might suppress proinflammatory cytokines such as tumor necrosis factor (TNF)-α, IL-1β and IL-6, which are involved in the inflammation and pathogenesis of asthma." (PMID 32143340, 2020). "In asthma mouse model, anti-TNF-α treatment attenuated airway inflammation." (PMID 32929606, 2020). "However, PBMCs from stable asthma patients upon exposure to the three BioPM showed more extreme TNFα responses than those from healthy subjects." (PMID 32620109, 2020). "In addition, OBE treatment decreased the pro-asthma TNF-α but increased the Th2 anti-inflammatory cytokine, IL-10." (PMID 33123005, 2020). "In the peripheral blood of children with asthma, the possibility of intestinal flora disorders and gastrointestinal discomfort symptoms increases, with the elevation in the levels of inflammatory factors such as TNF-α and IL-6." (PMID 33456673, 2020). "Thus, we investigated the effects of the methanol extract of LOL on OVA-challenged asthma murine model and TNF-α-stimulated NCI-H292 cells." (PMID 32605045, 2020). "The upregulated expression levels of IL-1β, IL-6, IL-12, IL-17A, KC, MCP-1 and TNF-α may contribute to airway neutrophilia and asthma exacerbation." (PMID 31889961, 2019). "Th17-related cytokines such as TNF-α, IL-6, and IL-1β are important in the control of asthma onset." (PMID 31790411, 2019). "Similar phenomenon of TNF-α induced potentiation of Ca2+ current evoked by TRPV1 has been reported in rat pulmonary sensory neurons in asthma, in cultured trigeminal ganglions isolated from neonatal rats, in human synoviocytes and in sensitization of the spinal cord in the pain model." (PMID 31632242, 2019). "In addition to generating T helper cell type 2 (Th2) immune responses, Th1-predominant inflammatory factors such as tumor necrosis factor (TNF)-α are elevated in asthma patients." (PMID 31061451, 2019). "In study I, we confirmed the different clinical characteristics of EA, NA and PGA phenotypes, and as in previous studies showed that subjects with NA were older, had longer asthma durations, and higher sputum IL-1β, IL-8 and TNF-α, but lower FENO compared with EA." (PMID 31113430, 2019). "The level of TNF-α increased in the lung tissue of the asthma group (P < 0.001)." (PMID 32641957, 2019). "Dexa and MYR reduced the levels of TNF-α compared to the asthma group (P < 0.01)." (PMID 32641957, 2019). "Increased levels of TNF‐α have been described in the airways of patients with severe asthma." (PMID 30666647, 2019). "Prior researches demonstrated that TNF-α −863A allele may reduce the risk of chronic obstructive pulmonary disease (COPD) and asthma." (PMID 31652851, 2019). "TNF was found to be involved in the development of allergic diseases, particularly asthma." (PMID 30038057, 2018). "Th17 cells produce some pro-inflammatory cytokines, particularly IL-17A, IL-17F, IL-21, IL-22, TNF-α, and GM-CSF, which may have important roles in the reinforcement of severe form of asthma." (PMID 30116273, 2018). "The effects of TNF-α in corticosteroid-resistant asthma may be mediated by direct effects to alter the dynamics of the Ca2+ response to agonists and thereby the contractility of the ASM." (PMID 29576747, 2018). "Compared with the control group, the relative expression levels of miR-1 and IFN-γ in the peripheral blood of children with asthma in the study group were significantly decreased, whereas the expression levels of IL-4, IL-5, IL-8, and TNF-α were significantly increased." (PMID 30046607, 2018). "Anti-TNF-α drugs could improve lung function, airway hyperresponsiveness, and reduce exacerbation frequency in patients with severe asthma." (PMID 29751569, 2018). "With asthma exacerbation, Th1 T cells were recruited and they secreted TNF-α and interferon." (PMID 29751569, 2018).